GRPR (gastrin releasing peptide receptor)
Diseases named in the same sentence as GRPR in open-access papers (continued):
Sharing a sentence is not in itself a finding about the gene and the disease.
tumor (continued). "All three tracers showed high uptake in PC-3 tumor xenografts (11.4 to 15.7%ID/g) and much lower accumulation in the pancreas (1.98 to 8.99%ID/g) at 1 h post-injection, suggesting their potential for detecting GRPR-expressing cancer lesions." (PMID 40283887, 2025). "Only the radioiodinated heterodimer 125I-BO530, which combines a PSMA-targeting urea-based inhibitor with a GRPR antagonist (RM26), linked via a PEG2 linker, demonstrated high affinity for both receptors and high tumor uptake (~30–35% ID/g at 3 h), which was sustained up to 24 h." (PMID 40869454, 2025). "Among the three new [99mTc]Tc-DB15-base analogues designed to accommodate trivalent radiometals for theranostic use, [111In]In-AU-SAR-M1 turned out to be the most promising, owing to its high GRPR-specific tumor uptake and retention in combination with a low and declining uptake in healthy tissues." (PMID 38366299, 2024). "This suggests that [68Ga]Ga-LW02075 might have a higher binding affinity or be more selective toward the mouse GRPR expressed by the mouse pancreas than the human GRPR expressed by the PC-3 tumor xenografts." (PMID 38999054, 2024). "The development of GRPR-targeted radiopharmaceuticals has been focused on using antagonist sequences as targeting vectors because of their potentially higher tumor uptake due to higher in vivo stability and more binding sites than those available for agonists, and/or less short term adverse effects." (PMID 38305955, 2024). "Our results demonstrate that most GIST tumours exhibit a moderate to high expression of the receptor, suggesting that GRPR theranostics could be a viable option for TKI-resistant GIST." (PMID 41646945, 2024). "Although antagonists are preferable for the development of GRPR-targeted radiopharmaceuticals due to potentially fewer side effects, internalization of agonists may lead to longer tumor retention and better treatment efficacy." (PMID 38305955, 2024). "Interestingly, tumours that were pretreated with TKI showed lower expression levels of GRPR, indicating a need for further studies to explore this finding." (PMID 41646945, 2024). "Among the proteins successfully targeted by functionalized lanthanide nanoparticles are folic receptors, fibroblast activation protein (FAP), gastrin-releasing peptide receptor (GRP-R), prostate-specific membrane antigen (PSMA), and integrins associated with tumor neovasculature." (PMID 38334567, 2024). "In this study, we systematically investigated unnatural amino acid substitutions to improve in vivo stability and tumor uptake of a previously reported GRPR-targeted agonist tracer, [68Ga]Ga-TacBOMB2 (68Ga-DOTA-Pip-D-Phe6-Gln7-Trp8-Ala9-Val10-Gly11-His12-Leu13-Thz14-NH2)." (PMID 38305955, 2024). "Tumor specimens were subjected to GRPR immunohistochemical staining." (PMID 38279185, 2024). "This also indicates that, by using the Ga-TacsBOMB2 pharmacophore, the combination of αMe-Trp8 or NMe-Gly11 substitution with Tle10 substitution cannot further improve either the binding affinity to GRPR or increase the uptake in GRPR-expressing PC-3 tumor xenografts." (PMID 38794191, 2024). "Moreover, GRPR, which is predominantly expressed in the tumor core, exhibited correlation patterns similar to those of PSMA." (PMID 39629134, 2024). "Additionally, H&E staining of lung tissues revealed a reduction in metastatic tumor regions in mice with GRPR-silenced cells." (PMID 39768218, 2024). "The expression of GRPR correlates with tumor grade stage, and other factors." (PMID 38708130, 2024). "Therefore, blockade of GRPR signaling using low dose of IRye800‐RM26 (10 μM) inhibited tumor cells invasion." (PMID 37476052, 2023). "Their results showed that the GRPR/integrin αvβ3 bispecific tracer ([18F]FB-BBN-RGD) achieved higher tumor uptake and tumor-to-background contrast ratios than both of its corresponding monospecific tracers ([18F]FB-BBN for GRPR and [18F]FB-RGD for integrin αvβ3)." (PMID 36770755, 2023).
tumor (continued). "We and others have shown that AuNPs functionalized with bombesin derivatives were able to specifically deliver imaging (e.g., 67Ga) and therapeutic radionuclides (e.g., 198Au and 177Lu) to tumor cells overexpressing the gastrin releasing peptide receptor (GRPR) 24-29." (PMID 36593794, 2023). "Similar to [68Ga]Ga-TacsBOMB2 and [68Ga]Ga-TacsBOMB3, the derived [68Ga]Ga-TacBOMB2 and [68Ga]Ga-TacBOMB3 agonist PET tracers also retain in vivo GRPR-targeting capabilities, as demonstrated by their good tumor uptake and tumor-to-background contrast ratios in imaging and biodistribution studies." (PMID 36838968, 2023). "Although studies with GRPR radiopharmaceuticals, including NeoB, have demonstrated high uptake not only in the tumor, but also in the GRPR-expressing pancreas, multiple studies have shown that the pancreas is not expected to be a dose limiting organ for GRPR-mediated treatment." (PMID 37719014, 2023). "Currently, a phase I/IIa clinical trial (NeoRay, NCT03872778) is ongoing in which the safety, tolerability, pharmacokinetics, distribution, radiation dosimetry, and anti-tumor activity of [177Lu]Lu-NeoB are investigated in patients with tumors known to overexpress GRPR." (PMID 37584725, 2023). "The heterogeneity of the receptor expression within the tumour and the unevenness regarding the radiopharmaceutical binding ability of GRPR could underpin the difference between the tracer accretion of the external and inner tumour regions." (PMID 37108559, 2023). "Furthermore, given the high expression of GRPr in several cancer types, it is a relevant pan-tumor target for RLT." (PMID 38201600, 2023). "Such PSMA/GRPR-radioligands could increase the chance of specific binding to tumours and thereby promote the detection accuracy for patients with a non-homogenous expression of either of the targets." (PMID 36672390, 2023). "For example, [111In]In-SB4, where Gly11 is replaced by DAla11, despite its high in vivo metabolic stability demonstrated lower GRPR-affinity and cell uptake, eventually translating into an inferior tumor uptake compared with the unmodified parent [111In]In-SB3." (PMID 37509170, 2023). "This comparative study was expected to address how the GRPR-targeting strategy would influence the selectivity of cytotoxic effects (i.e., between tumor and non-tumor cells), and the induced mechanisms of cell death, namely through ROS production and cell apoptosis." (PMID 36593794, 2023). "The in vivo GRPR-targeting specificity study for [111In]In-AU-RM26-M1 in mice bearing PC-3 tumors (GRPR-positive) showed a significant reduction in tumor activity uptake in the GRPR-blocking group at 1 h pi (0.9 ± 0.6%IA/g vs. 7.0 ± 0.7%IA/g for controls; p < 0.001, n = 4)." (PMID 37509170, 2023). "Moreover, the suppression of the BBN/GRPR axis leads to the inhibition of tumour propagation and vascularization." (PMID 37108559, 2023). "This indicates that the slightly higher tumor uptake of [68Ga]Ga-AMBA may also owe to its better in vivo stability other than its better binding affinity toward GRPR." (PMID 36838968, 2023). "Interestingly, radiolabeled GRPR antagonists also demonstrated high tumor accumulation in vivo and even superior pharmacokinetic properties, mainly due to their faster clearance from pancreas and non-target organs." (PMID 38020178, 2023). "Besides modulating the morphology of neoplastic cells, tumour differentiation, and tumour proliferation, activated GRPR catalyses the overexpression of proangiogenic genes." (PMID 37108559, 2023). "The specificity of the PC-3 tumor uptake (GRPR-positive) was further confirmed by the significantly lower uptake of the radioligand in the DU-145 tumors (GRPR-negative) that was at the same level as the GRPR-blocked group." (PMID 37509170, 2023).
tumor (continued). "Moreover, radiolabeled GRPR antagonists have frequently displayed superior pharmacokinetics compared to agonists, combining a higher tumor uptake with a faster body clearance, resulting in higher tumor-to-background ratios." (PMID 37509170, 2023). "At 3h pi, increased tumour-to-organ ratios could be seen due to higher retention in the tumor compared with other PSMA or GRPR-expressing organs." (PMID 36672390, 2023). "In T47D xenografts, the radiotracer showed high metabolic in vivo stability and prolonged GRPR-specific uptake (14.01 ± 2.87% IA/g at 1 h p.i. and 7.55 ± 1.81% IA/g at 24 h p.i. in the tumor and 130% IA/g at 1 h p.i. and approx. 2% IA/g at 24 h p.i. in the pancreas)." (PMID 38020178, 2023). "Results from the biodistribution study in PC3-pip xenografted mice showed specific binding to both targets, with the highest activity uptake at 1 h pi in tumor (PSMA+/GRPR+, 10.4 ± 1.0% IA/g), kidneys (PSMA+, 45 ± 16% IA/g), and pancreas (GRPR+, 5.6 ± 0.7% IA/g)." (PMID 36672390, 2023). "In addition, other reports have shown the expression of GRPr in metastatic lymph nodes, bones, and advanced tumor stages, suggesting the clinical potential of GRPr as a target for PET imaging and RLT and as an alternative to PSMA." (PMID 38201600, 2023). "During recent years, properly tailored BBN-like peptides have been proposed as theranostic anti-cancer agents, capable of delivering diagnostic (gamma/positron emitting) radionuclides or therapeutic payloads (beta− and alpha particle emitters) to GRPR-expressing tumor lesions." (PMID 37242457, 2023). "All 99mTc-labeled MJ9 derivatives revealed similarly low activity levels in all organs (<4.5 percent injected dose per gram; %ID/g), except for the GRPR-positive pancreas (4.7–39.0 %ID/g) and the PC-3 tumor (9.3–14.6 %ID/g) at 1 h p.i., which indicates a rapid clearance from off-target tissues." (PMID 36145354, 2022). "The significant overexpression of GRPR in various malignant tumor tissues makes it a very attractive target, whereby carborane could be attached to the peptide conjugates targeting tumor cells through GPCRs overexpressed on cancer cell membranes." (PMID 35141397, 2022). "Extensive research has been carried out on probes targeting the prostate-specific membrane antigen (PSMA), but it has been suggested that GRPR-targeted imaging probes may be of great value for PSMA-negative tumor lesions." (PMID 35057090, 2022). "Furthermore, in the pretargeting experiment, the tumor and pancreas uptake at 1 h post-injection were reduced upon GRPR blockade with a BBN agonist, from 1.19 ± 0.2 to 0.64 ± 0.1%I.D./g and from 0.4 ± 0.11 to 0.25 ± 0.05%I.D./g, respectively." (PMID 36559063, 2022). "Tumor uptake was GRPR-specific and exceeded normal organ uptake." (PMID 33574368, 2021). "It is unclear whether antiestrogens also affect GRPR expression and, thus, tumor visualization by [68Ga]RM2." (PMID 34885214, 2021). "Moreover, several authors studied the correlation between GRPR overexpression in PC tissues and the tumor grade or stage, leading to different results." (PMID 33672425, 2021). "Thus, absorbed doses in tumor lesions were found to be therapeutically relevant, whereas rapid clearance from normal GRPR-rich organs was confirmed, such as the pancreas, considered to be the dose-limiting organ due to its high radioligand uptake." (PMID 34830920, 2021). "In a recent innovative approach, prolonged tumor retention could be achieved in mice models when using GRPR peptide radioligands, either agonists or antagonists, modified with cysteine cathepsin inhibitors, via an endolysosomal trapping mechanism." (PMID 34830920, 2021). "Although GRPR radioantagonists turned out to be typically more stable than their agonist-based counterparts, notable tumor uptake improvements could still be observed in most cases, providing new exciting prospects for better diagnosis and therapy." (PMID 34830920, 2021).
tumor (continued). "Higher tumor-to-background ratios have been achieved, in preclinical studies, with the application of higher peptide doses, an approach potentially applied in humans only for GRPR antagonists owing to biosafety concerns." (PMID 34830920, 2021). "NeoB is undergoing evaluation as a novel theragnostic agent—that is, that it can be employed either for the diagnosis of tumor expressing gastrin-releasing peptide receptor (GRPR) using nuclear imaging, or for the therapy of such GRPR positive tumors using internal radiotherapy." (PMID 33801382, 2021). "Previous studies have found a significant inverse correlation between GRPR and several indices of tumor growth (GS, PSA and tumor size), on the other hand, we focused on low grade PC with neuroendocrine differentiation as indicated by the relationship between GRPR and PSMA." (PMID 33854977, 2021). "Highly expressed GRPR was also observed in tumor endothelial cells." (PMID 33532584, 2021). "A fully GMP compliant kit preparation of [68Ga]Ga-NeoB enabling the routine production of the tracer under GMP conditions was established for clinical routine PET/CT imaging of patients with metastatic GIST and proved to adequately visualize tumor deposits in the abdomen expressing GRPR." (PMID 34228236, 2021). "We could also observe specific radioligand uptake in two GRPR-positive tumor animal models, namely, in human prostate PC-3 and breast T-47D cancer xenografts in immunosuppressed mice combined with a rapid background clearance." (PMID 34680243, 2021). "In summary, these peptide-based radiopharmaceuticals, which retain binding specificity to GRPR, demonstrated high yields, high stability, high tumor uptake, and rapid clearance of radioactivity from blood or physiologic non-GRPR-expressing organs in rodent models and humans." (PMID 33335885, 2020). "A stable and selective GRPR-agonist could potentially feature similar or even better tumor uptake values compared to antagonists." (PMID 32733853, 2020). "We demonstrated among other things that, despite high and specific tumor uptake, different macrocyclic chelators’ charges and structures have a strong influence on the binding affinity of the GRPR-targeting peptide and activity retention time, both in tumors and normal tissues." (PMID 33352838, 2020). "There were also tumor regions where PSMA-PET showed a higher signal than GRPR in 4/8 patients." (PMID 32533273, 2020). "The study showed that 68Ga-HEn (n = 0–3) could synergistically target PSMA and GRPR on LNCaP and PC-3 PCa cells and tumor xenografts." (PMID 33335885, 2020). "Furthermore, the tumor uptake of [68Ga]Ga-14 correlated well with GRPR and αvβ3 expression, demonstrating the bispecificity of the tracer and the synergistic effects of heterobivalency." (PMID 32751666, 2020). "This discrepancy between the uptake in tumor and GRPR-expressing organs was previously reported for the same conjugates labeled with 111In16 and for other radiolabeled bombesin analogues and is most likely due to differences in affinity towards human and murine GRPR." (PMID 31745219, 2019). "Interestingly, despite similar tumor uptake, the activity accumulation in GRPR-expressing organs differed significantly between conjugates." (PMID 31745219, 2019). "As a whole, 99mTc-BN4 has emerged out as the most promising GRPR-positive tumor imaging probe." (PMID 30887136, 2019). "From the H&E and IHC, elevated levels of GRPR in the mice tumor tissue section were found." (PMID 30887136, 2019). "Furthermore, it was demonstrated that bombesin-based GRPR antagonists have more binding sites than agonists, which should be beneficial for tumor uptake." (PMID 31540122, 2019). "Aiming to explore the effects of peptide chain as well as NEP inhibition on the pharmacokinetics and tumor targeting capabilities of the two tracers, we have conducted biodistribution experiments in immunosuppressed mice bearing human GRPR-expressing xenografts." (PMID 30897789, 2019).
tumor (continued). "Moreover, recent studies have shown that radiolabeled GRPR-antagonists unexpectedly achieved superior tumor targeting and better pharmacokinetics compared to their agonist counterparts." (PMID 30871262, 2019). "GRPR agonists demonstrated the lowest tumor-to-organ ratios." (PMID 31745219, 2019). "Increased internalisation of drug-loaded GRPR targeted liposomes in treatment-resistant tumours such as SCLC could offer improved therapeutic outcomes." (PMID 31921534, 2019). "However, GRPR antagonists tend to be considered superior to agonists for tumor imaging, with favorable in vivo characteristics." (PMID 31394799, 2019). "The new labeled heterodimer provided high contrast PET and SPECT images of PSMA/GRPR-positive xenografts shortly after administration (1–3 h) due to rapid blood clearance, high tumor uptake, and low uptake in normal tissues and excretory organs, including PSMA-expressing kidneys." (PMID 31540122, 2019). "Moreover, research has demonstrated that GRPR antagonists are usually superior to agonists for tumor targeting, in addition to exhibiting less adverse events." (PMID 29556947, 2018). "The fact that the effects on GRPR and αvβ3 integrin expression in tumors were observed at 8 h post hyperthermia is related to the time the dormant tumor cells (in autophagy) need to trigger the pathophysiological pathways for metabolic restoration in the sense of “hormesis”." (PMID 28761146, 2017). "In this context, changes of GRPR and αvβ3 integrin expression could be used to identify a potential reorganization of tumor regrowth." (PMID 28761146, 2017). "The GRPR targeting probe accumulated mainly in the tumor and kidney (8 days post treatment)." (PMID 28761146, 2017). "Highest signal intensities for GRPR were mostly found at the tumor periphery 8 days post treatment." (PMID 28761146, 2017). "For example, a GRPR inhibitor might have an effect on tumor cell proliferation, since GRPR stimulates tumor growth." (PMID 28761146, 2017). "Notably, at the 200 pmol peptide dose, the uptake in the GRPR-rich mouse pancreas was significantly reduced (from 206.29 ± 17.35% ID/g to 42.46 ± 1.31% ID/g; p < 0.001), whereas tumor levels remained unaffected." (PMID 29137110, 2017). "In view of contradictory results, with GRPR being up-regulated in tumor cell secretome while down-regulated in PDAC patient serum, the reliability of the marker could be questioned." (PMID 28060763, 2017). "Interestingly, GRPR expression in isolated tumor cells was particularly prominent in those cell populations which were exposed to comparatively high temperature doses." (PMID 28761146, 2017). "In contrast, 99mTc-RGD-BBN imaging had a clear tumor uptake due to the function of GRPR." (PMID 25849333, 2015). "In addition to relatively higher distribution in PC3 tumor tissue, ProCA1.GRPR was also largely distributed in liver and kidney." (PMID 26577829, 2015). "The uptake of 99mTc-3P4-RGD2 by tumor with both integrin αvβ3 and GRPR positive expression may be higher than 99mTc-RGD-BBN if more integrin αvβ3 are expressed." (PMID 25849333, 2015). "Thus, our developed MRI contrast agent ProCA1.GRPR enables real time visualization of the differential spatial distribution of GRPR that depends on tumor types and tissue organization." (PMID 26577829, 2015). "It is therefore proposed that in the first instance, patients with tumours that express the GRPR and another neuropeptide receptor who have failed conventional treatment should be randomised into two groups – best supportive care and treatment with substance P analogues." (PMID 12771999, 2003). "Therefore, future development of GRPR-targeted radiotherapeutic agents should focus on not only improving tumor absorbed dose to enhance treatment efficacy, but also increasing the tumor/pancreas absorbed dose ratio to minimize potential toxicity to the pancreas." (PMID 40283887, 2025).